CAPG (capping actin protein, gelsolin like)
Description:
Calcium-sensitive protein which reversibly blocks the barbed ends of actin filaments but does not sever preformed actin filaments. May play an important role in macrophage function. May play a role in regulating cytoplasmic and/or nuclear structures through potential interactions with actin. May bind DNA.
Synonyms: AFCP; MCP; HEL-S-66
Tractability: PROTAC: ubiquitination databases record sites on it; its protein half-life has been measured.
Safety:
Unwanted effects reported when the protein is acted on. In parentheses: how it was acted on, where the effect was seen, and who reports it.
grade 3-4 neurotoxicity (source: ClinPGx)
grade 3-4 neurotoxicity or grade 3-4 neurotoxicity (source: ClinPGx)
Gene: Protein-coding gene on chromosome 2 (85,393,587 to 85,422,017, reverse strand). Ensembl gene ENSG00000042493.
Subcellular location: Nucleus; Cytoplasm; Melanosome; Cell projection, lamellipodium; Cell projection, ruffle
Subcellular location (Human Protein Atlas): Nucleoplasm; Mitotic chromosome
Gene Ontology:
Molecular function: cadherin binding; protein binding; protein domain specific binding; protein-containing complex binding; phosphatidylinositol-4,5-bisphosphate binding; actin filament binding
Biological process: actin filament severing; actin polymerization or depolymerization; barbed-end actin filament capping; central nervous system development; protein-containing complex assembly
Cellular component: centriole; cytoplasm; extracellular exosome; Flemming body; melanosome; mitotic spindle; nucleolus; nucleoplasm; nucleus; F-actin capping protein complex; lamellipodium; ruffle
Genetic constraint (gnomAD): Loss-of-function variants: 31 observed, 44.17 expected, observed/expected ratio (o/e) 0.7, 90% interval 0.53 to 0.95. The upper end of that interval is the gene's LOEUF score, 0.95, which puts it in group 4 of 6, group 1 being the genes least tolerant of losing a copy. Missense variants: 401 observed, 437.18 expected, observed/expected ratio (o/e) 0.92, 90% interval 0.84 to 1. Synonymous variants: 170 observed, 180.32 expected, observed/expected ratio (o/e) 0.94, 90% interval 0.83 to 1.07.
Homologues: Orthologues: chimpanzee CAPG (99% identical), macaque CAPG (99% identical), guinea pig CAPG (94% identical), mouse Capg (93% identical), rat Capg (93% identical), dog CAPG (91% identical), rabbit CAPG (90% identical), pig CAPG (89% identical), zebrafish capgb (57% identical), zebrafish capga (56% identical), tropical clawed frog capg (51% identical), Drosophila melanogaster Gel (37% identical), and 1 more. Paralogues in human: GSN (49% identical), SCIN (47% identical), AVIL (43% identical), VIL1 (43% identical), VILL (36% identical), FLII (30% identical), SVIL (25% identical).
Diseases named in the same sentence as CAPG in open-access papers:
CAPG is named in the same sentence as 86 diseases in open-access papers, as found by Europe PMC text mining. Sharing a sentence is not in itself a finding about the gene and the disease. The quoted sentences say what the papers report.
breast carcinoma (29 papers, 2013 to 2025). "Research within our group previously identified actin capping protein (CapG) as a prognostic biomarker for risk of breast cancer spread to bone." (PMID 31488945, 2019). "In breast cancer patients, high CapG levels are significantly associated with poor response and short relapse-free survival (RFS) after chemotherapy treatment." (PMID 31660072, 2019). "Underlining its crucial role in tumor progression, CapG expression was found elevated at the tumor invasion front, the so-called interface zone, in breast cancer particularly." (PMID 24804218, 2014). "High CAPG expression is linked to breast cancer aggressiveness and prognosis and may encourage tumor cell growth and dissemination." (PMID 38700746, 2025). "Previously published studies have indicated that antimetastatic effects of Zol correlate with that tumour cell expression of the transcription factor MAF, whereas other studies have shown that high expression of GIPC1 and CAPG is associated with antitumour activity of Zol in breast cancer patients." (PMID 34733240, 2021). "Recognizing that migration and invasiveness play an important role, especially in high-grade ovarian carcinoma development, we focused our study on CapG, an actin binding protein that promotes cellular motility and has previously been associated with increased invasiveness in breast cancer." (PMID 24804218, 2014). "High CAPG expression correlates with shorter relapse‐free survival time and paclitaxel resistance in breast cancer." (PMID 39964147, 2025). "We showed that the addition of EGF increases nuclear shuttling of CapG in the breast cancer cells MDA-MB-231 within minutes." (PMID 39369027, 2024). "The promoter of CAPG is regulated by DNA methylation and is involved in integrin α6β4 regulating the invasion and metastasis of breast cancer cells." (PMID 39600941, 2024). "Serum-starvation doubled the number of breast cancer cells from 40 to 80% displaying increased CapG shuttling in response to EGF." (PMID 39369027, 2024). "(iii) CapG is expressed in fairly high amounts in the breast cancer cell so that repeated bleaching of the cell nucleus compartment and thereby a significant number of CapG-GFP molecules does not pose signal-to-noise problems." (PMID 39369027, 2024). "We previously showed a difference in CapG’s nuclear shuttling in cancer and normal cells as exemplified in the breast cancer cell line MDA-MB-231 and the nearly normal breast epithelial cells MCF-12A12." (PMID 39369027, 2024). "Upregulation of the STC-1 (stanniocalcin-1) gene by CapG in cancer cells enhances breast cancer metastasis." (PMID 37454739, 2023). "For example, the actin cytoskeleton protein CapG is usually overexpressed in breast cancer cells, where it appears to play a role in tumor cell dissemination and metastasis." (PMID 37631307, 2023). "In a breast cancer study, breast cancer cells expressing anti-CapG VHHs lost the capability of migration and invasion." (PMID 37746282, 2023). "Researchers have generated single-domain antibodies against CapG, a constituent of the actin cytoskeleton overexpressed in breast cancer, and used them as intrabodies to inhibit the interaction of CapG with actin." (PMID 38213543, 2023). "Tumor-bearing mice inoculated with breast cancer cells expressing anti-CapG VHHs showed significant slower tumor growth and prevention of lung metastasis compared to the control group." (PMID 37746282, 2023). "CapG exhibits faster nucleocytoplasmic shuttling in breast cancer cells than in normal breast epithelial cells as shown in a proof-of-principal study using quantitative live-cell microscopy." (PMID 36230711, 2022). "Increased CapG was found in human oral premalignant lesions and in the interface zone of breast cancer, the region between the invading tumor front and normal tissue, indicating CapG involvement in early carcinogenesis and margin invasion." (PMID 36258216, 2022).
breast carcinoma (continued). "As in other cells, CapG distributes diffusively in both the cell nucleus and cytoplasm of the highly invasive breast cancer cell line MDA-MB-231 and the nearly normal breast epithelial cell line MCF-12A." (PMID 36230711, 2022). "Beta-catenin in endometrial cancer and CapG in breast cancer are examples of differential protein distributions in normal and cancer cells." (PMID 36230711, 2022). "Previous studies propose that CapG is involved in the proliferation and metastasis of tumor cells and therefore can be considered as one of the drug targets in breast cancer." (PMID 35933373, 2022). "CapG is part of the actin filament, often overexpressed in breast cancer, and is believed to play a role in tumor cell metastasis." (PMID 34204007, 2021). "Attaching a nanoparticle that works against CapG to various CPPs has been shown to be an effective strategy in reducing breast cancer metastasis." (PMID 34204007, 2021). "The mechanistic role of these proteins within bone metastasis of breast cancer has recently been elucidated with the discovery that CAPG acts as an epigenetic regulator for the expression of a key pro-metastatic regulator." (PMID 32751181, 2020). "CapG expression in patients with adjuvant chemotherapy was studied in breast cancer resection specimens using IHC and related to pathological response and disease-free survival." (PMID 31660072, 2019). "To further explore the mechanisms involved in CapG-promoted PI3K/Akt signaling, we ectopically expressed CapG in breast cancer cells and examined its impact on PI3K/Akt activation." (PMID 31660072, 2019). "High CapG level also significantly correlated with shorter relapse-free survival as well as hyper-activation of PI3K/Akt signaling in breast cancer patients." (PMID 31660072, 2019). "The decreased Caspase 3 activation in paclitaxel-treated MCF-7/CapG xenograft tumors, compared with that in MCF-7 xenografts, further supported an anti-apoptotic role of CapG in paclitaxel-treated breast cancers, likely owing to increased PI3K/Akt activation." (PMID 31660072, 2019). "Overexpressing CapG significantly enhanced paclitaxel resistance in breast cancer cells and xenograft tumors." (PMID 31660072, 2019). "In accordance, we found the expression level of CapG correlated with PIK3R1/p50α levels in a panel of breast cancer cells." (PMID 31660072, 2019). "Altogether, these results indicate that CapG promotes resistance to PTX in breast cancer cells and knocking down of CapG was able to mitigate PTX resistance in breast cancer." (PMID 31660072, 2019). "CapG overexpression leads to increased proliferation and paclitaxel resistance in breast cancer cells." (PMID 31660072, 2019). "To further evaluate the clinical significance of CapG in breast cancer chemotherapy resistance, we assessed the level of CapG with immunohistochemistry (IHC) assay in a tissue array with a cohort of 200 primary breast cancer patients treated with chemotherapy." (PMID 31660072, 2019). "CAPG gene transcription was significantly increased in breast cancer cells acquired resistance to chemotherapy." (PMID 31660072, 2019). "We found CapG specifically promoted PIK3R1/P50 isoform transcription in breast cancer cells, which subsequently triggered activation of PI3K/Akt signaling, resulting in increased cell growth and decreased apoptosis in breast cancer cells exposed to paclitaxel." (PMID 31660072, 2019). "All these data suggest that increased CAPG levels render breast cancer cells more resistant to PTX treatment." (PMID 31660072, 2019). "Consistently, CapG expression positively correlated with the level of Akt phosphorylation in breast cancer TCGA-RPPA dataset." (PMID 31660072, 2019). "In this study, we show for the first time that CapG contributes to chemotherapy resistance especially paclitaxel resistance in breast cancer by epigenetically enhancing PIK3R1/P50 transcription, resulting in increased activation of PI3K pathway." (PMID 31660072, 2019).
breast carcinoma (continued). "As we recently showed that CapG enhances breast cancer metastasis 28, we decided to focus our further investigation on the role of CAPG in promoting PTX resistance." (PMID 31660072, 2019). "In this study, we show that CapG promotes resistance to chemotherapy, especially paclitaxel resistance, in breast cancer by activating PI3K signaling." (PMID 31660072, 2019). "To validate the role of CapG in paclitaxel resistance in vivo, we generated orthotopic mammary tumors model with MCF-7/Control or MCF-7/CapG cells." (PMID 31660072, 2019). "Perturbing the interaction between CapG and actin strongly reduces breast cancer metastasis in immunodeficient mice." (PMID 24330716, 2013). "We raised single-domain antibodies (nanobodies) against human CapG and used these as intrabodies (immunomodulation) after lentiviral transduction of breast cancer cells." (PMID 24330716, 2013). "Our findings show that nanobody-based protein-directed CapG inhibition (immunomodulation) strongly reduces breast cancer metastasis, arguing against CapG redundancy." (PMID 24330716, 2013). "In recent years, several proteomic studies demonstrated that CapG is overexpressed in various types of cancer, including breast cancer." (PMID 24330716, 2013). "We expressed EGFP-tagged nanobody cDNAs in MDA-MB-231 breast cancer cells by lentiviral transduction to verify their ability to act as bona fide CapG binders in the cytoplasmic environment (as intrabodies)." (PMID 24330716, 2013). "Proteomic studies have demonstrated overexpression of CapG, a constituent of the actin cytoskeleton, in breast cancer." (PMID 24330716, 2013). "For example, in tumors such as breast cancer and lung cancer, high expression of CAPG may be related to the malignancy and poor prognosis of the tumor." (PMID 38700746, 2025). "Thus, repeated FRAP of CapG in the cell nucleus can be used as functional readout of signaling cascades in the same single live breast cancer cell." (PMID 39369027, 2024). "Notably, treatment of breast cancer cells with a CapG-specific nanobody conjugated to various CPPs effectively reduced breast cancer metastasis by blocking CapG activity." (PMID 37631307, 2023). "Notably, Huang S. and colleagues reported that CapG functions as a transcription factor in breast cancer." (PMID 37454739, 2023). "Likewise, another study involving breast cancer cells expressing anti-CapG VHHs also raises the same concerns." (PMID 37746282, 2023). "CAPG could play a significant role in the survival of breast cancer, bladder cancer, as well as ovarian cancer, and many more." (PMID 36723760, 2023). "They produced nanobodies against human CapG and used them as intrabodies in breast cancer cells." (PMID 35933373, 2022). "Furthermore, 34.4% of the proteins were reported to be associated with other cancers, including macrophage-capping protein (CAPG), which is a as breast cancer biomarker, and perilipin-2 (PLIN2), which is a renal cell carcinoma biomarker." (PMID 32675193, 2020). "Since inhibiting CBP/p300 by C646 also substantially decreased PI3K/Akt activation by CapG overexpression in breast cancer cells, targeting CBP/p300 may serve as an alternative strategy to counteract CapG-mediated paclitaxel resistance." (PMID 31660072, 2019). "Nevertheless, whether the nuclear CapG directly regulates gene transcription and its pathological roles in promoting breast cancer progression are largely unknown." (PMID 31660072, 2019). "Nevertheless, whether the actin-capping activity of CapG is involved in therapy resistance in breast cancer cells remains to be further determined." (PMID 31660072, 2019). "Altogether, our findings support that CapG may serve as a novel predictor of taxane chemotherapy outcome in breast cancer patients, as well as a potential therapeutic target for mitigating resistance to chemotherapies." (PMID 31660072, 2019). "Targeting CapG-mediated hyperactivation of PI3K/Akt pathway may mitigate resistance to chemotherapy in breast cancer." (PMID 31660072, 2019).
breast carcinoma (continued). "Considering that PI3K/Akt signaling activation has been shown to promote therapy resistance in breast cancers 31-33, these data suggested that CapG may promote drug resistance through modulating PI3K/Akt signaling pathways in breast cancer cells." (PMID 31660072, 2019). "Then CapG expression level was detected in a series of breast cancer cells." (PMID 31660072, 2019). "Altogether, our findings strongly indicate that high CapG levels may serve as a novel biomarker for predicting primary and acquired resistance to chemotherapy in breast cancer patients." (PMID 31660072, 2019). "Tam-loaded PVP–PLGA NPs and herceptin-conjugated Tam-loaded PVP–PLGA NPs, which target HER2, have been found to treat multi-drug-resistant breast cancer, and the Nb targeting F-actin capping protein CapG inhibits cancer metastasis in animal models of breast cancer." (PMID 28469136, 2017). "In this study, we used llama-derived CapG single-domain antibodies or nanobodies in a breast cancer metastasis model to address whether inhibition of CapG activity holds therapeutic merit." (PMID 24330716, 2013). "In this study, we used anti-CapG nanobodies as a tool to question whether the actin-binding properties of CapG are redundant at the protein level in a breast cancer metastasis model." (PMID 24330716, 2013). "Furthermore, NK(CAPG) also promotes colorectal cancer and breast cancer." (PMID 36046723, 2022). "Since hyper-activation of PI3K/Akt signaling has been shown as a shared mechanism responsible for resistance to multiple chemotherapeutic drugs 41, 52-54, we envision that high CapG level may have potential clinical value of predicting poor response to chemotherapy in breast cancer patients." (PMID 31660072, 2019). "Taken together, our study supports that CapG may serve as a promising molecular biomarker to predict chemotherapy resistance as well as a potential therapeutic target for improving chemotherapy response in breast cancer." (PMID 31660072, 2019). "Therefore, selective upregulating of PIK3R1/p50α, instead of p85α, by CapG may lead to more efficient activation of PI3K/Akt activation in breast cancer cells." (PMID 31660072, 2019). "Importantly, our finding was consistent with previous findings in human glioma, breast cancer, gastric cancer, and ovarian cancer, suggesting that CapG could be an oncoprotein." (PMID 30155403, 2018). "The assays confirmed that CREB3L1, CAPG, and SPINT1 were significantly upregulated in breast cancer group, while GRK3 was significantly downregulated when compared to normal group, respectively." (PMID 39015775, 2024). "To detect changes in CapG’s nucleocytoplasmic shuttling in response to external stimuli on the single cell level, we established repeated FRAP experiments of one and the same breast cancer cell." (PMID 39369027, 2024). "PRMT5 directly binds to CAPG, and CAPG regulate STC-1 transcription by competing with PRMT5 to enhance breast cancer metastasis." (PMID 34513846, 2021). "All these results support a transcription regulatory role of nuclear CapG in promoting activation of PI3K/Akt signaling pathway, thereby contributing to the chemotherapy resistance in breast cancer cells." (PMID 31660072, 2019). "All together, these data strongly support that CapG promotes paclitaxel resistance through activating the PI3K/Akt signaling pathway, which enhances proliferation and attenuates apoptosis in breast cancer cells exposed to paclitaxel." (PMID 31660072, 2019). "Consistently, inhibiting p300/CBP substantially decreased CapG-dependent upregulation of PIK3R1/P50 and subsequent PI3K/Akt activation, resulting in increased sensitivity to paclitaxel treatment in breast cancer cells." (PMID 31660072, 2019). "In Western blot experiments, several nanobodies belonging to different classes specifically recognized a ~40-kDa protein, corresponding to CapG, present in protein extracts obtained from MDA-MB-231 breast cancer cells." (PMID 24330716, 2013).